NLRP3 (NLR family pyrin domain containing 3)
Diseases named in the same sentence as NLRP3 in open-access papers (continued):
Sharing a sentence is not in itself a finding about the gene and the disease.
infection (continued). "The activation of NF-κВ pathway and NLRP3 inflammasome during infection leads to upregulation of pro-inflammatory cytokines expression." (PMID 36726689, 2023). "Shed P2X7R (sP2X7R) and shed NLRP3 (sNLRP3) have been detected in plasma and other body fluids, especially during infection and inflammation." (PMID 37215142, 2023). "NLRP3, IL-1β and TNFα levels were increased more in mice during infection when the virus carried the virulence marker of K627 compared to that of E627." (PMID 37465759, 2023). "The demonstration here that human, bacterial and fungal derived NDPKs converge on signaling via a common TLR4-independent NLRP3 inflammasome pathway, has implications for the role of infections in AML and MDS progression." (PMID 37418424, 2023). "This difference decreases in NLRP3 knockout C57BL6 mice, suggesting NLRP3 and IL-1β protect against L. guyanensis-infection (de Carvalho RVH, Lima-Junior DS, 2019)." (PMID 37276232, 2023). "The percentage of speck positive cells and the colocalization of NLRP3 with ASC were lower after hvKp infection compared with that after cKp infection." (PMID 37457695, 2023). "It has been reported that NLRP3 is activated by different pathogens, such as Mycobacterium tuberculosis (M.tb), Staphylococcus aureus, and Clostridium septicum, and NLRP3 plays an important role in protecting the host against infection." (PMID 37684678, 2023). "NOD-like receptors also play a vital role in the infection of various pathogens and the process of intrinsic immunity, for example, NLRP3." (PMID 37168122, 2023). "The Achromobacter strains induced pyroptosis by engaging either the NLRC4 or NLRP3 sensors, as demonstrated by infections in THP-1 cells with single and double knockouts in these sensors." (PMID 37598340, 2023). "The NLRP3 inflammasome is a component of the inflammatory response to infection and injury, orchestrating the maturation and release of the pro-inflammatory cytokines interleukin-1β (IL-1β), IL-18, and triggering pyroptotic cell death." (PMID 38129373, 2023). "In response to infection, there was a significant, Ch25h-dependent increase in Nlrp3, Pycard, and Casp1 gene expression observed at 24 h post-infection." (PMID 36831236, 2023). "Our results are in agreement with recent report revealing that pharmacological inhibition of NLRP3 inflammasome with MCC950 or knockout of NLRP3 abrogate both SARS-CoV-2 replication and associated inflammation during infection of human ACE2 mice." (PMID 37920468, 2023). "Consistently, on day 11 after infection, extensive collagen was deposited in the alveoli and lung interstitium of Nlrp3−/− and Caspase1−/− mice, whereas only minor collagen deposition occurred in the alveoli of WT mice." (PMID 37376638, 2023). "MCC950 selectively inhibits NLRP3, reduces the formation of the shear body, inhibits the maturation of IL‐1 and IL‐18, and reduces the range of infection‐induced cardiac dysfunction (IICD) and fibrosis." (PMID 37249295, 2023). "Neither ASC nor NLRP3 played a significant role in host defense against ST infection, and IL-18 release was unaffected in infected Nlrp3-/—mice." (PMID 37155697, 2023). "Baicalein attenuated infection-mediated acute liver injury by blocking NLRP3/GSDMD-mediated pyroptosis." (PMID 38022612, 2023). "The increased secretion of IL-1β and concomitant activation of NLRP3 has also been observed upon infection with tissue and blood parasites." (PMID 37375100, 2023). "Activation of complex signaling cascades such as the NLR family pyrin domain containing 3 (NLRP3) inflammasome can be triggered by a wide range of factors including cellular stress, infection, protein aggregates, and activated microglia." (PMID 36950516, 2023). "NLRP3 inflammasome is a multiprotein complex that orchestrates innate immune responses to infection and cell stress, and NLRP3 inflammasome is activated in response to diverse stimuli." (PMID 37228386, 2023).
infection (continued). "The infection did not significantly change Nlrp3 expression in colonic tissue, while higher Nlrp3 levels were detected in the hepatic tissue after infection with the MC1 TT strain." (PMID 38274797, 2023). "Here we found that Nlrp3−/− mice showed defective expression of Ifna1, and bore significantly higher titer of virus in the lung compared to WT mice 3 days after infection." (PMID 36746963, 2023). "We therefore conclude that selective usage of NLRP3 more closely resembles the activation state of neutrophils during infection and inflammation." (PMID 37730693, 2023). "And NLRP3 inflammasome is critical in the maintenance of homeostasis against pathogen infections and plays a dual role, as the secretion of inflammatory cytokines and cell pyroptosis can cause tissue damage at the same time of pathogen clearance." (PMID 37817895, 2023). "To determine the effect of NLRP3 inhibition in viral replication, we determined the viral titer in supernatants obtained from the infection assays of the bovine macrophages." (PMID 37515181, 2023). "The phagocytosis of disease- and infection-related protein or peptide aggregates by macrophages, is a well characterized inducer of NLRP3 inflammasome activation." (PMID 37950278, 2023). "It is also important to note that, during in vivo infection exfoliation of infected superficial bladder epithelial cells from urinary bladder is dependent on the NLRP3 inflammasome." (PMID 37697284, 2023). "CL exposure in the mitochondrial membrane is a known damage signal inducing mitophagy, and in the context of infection (NLRP3 priming) it constitutes a danger signal." (PMID 38077364, 2023). "Next, we compared the infections of WT, Nlrp3–/–, Gsdmd–/–, and Casp1/11–/– mice using metacyclic promastigotes." (PMID 36828815, 2023). "The NLRP3 inflammasome is an innate immune multiprotein complex chiefly triggered by pathogen infection and cellular damage." (PMID 38058609, 2023). "Most of the genes in this gene ontology showed higher expression in Cas9 cells compared to NLRP3-deficent cells after CFT073 infection." (PMID 37759520, 2023). "As a result, researchers have begun to explore strategies to modulate NLRP3 inflammasome activity to alleviate infection-induced pathology." (PMID 37376638, 2023). "The activation of the NLRP3 inflammasome during sublethal IV infection performs a substantial function in limiting lung damage resulting from infection." (PMID 37773712, 2023). "The potential for therapeutic interventions to mitigate the inflammatory response induced by HIV-1 exposure and productive infection, such as targeting ATP efflux or the NLRP3 inflammasome, will be examined." (PMID 37325659, 2023). "Here, we consistently demonstrate that environment-mediated increases in A20 expression exhibit NLRP3 inflammasome suppression and IL-1beta expression downregulation upon infection with IAV or LPS stimulation, which is consistent with previous reports." (PMID 36726689, 2023). "After WT W24 strain infection, NLRP3, caspase-1, GSDMD-N, and other factors in the classical pyroptosis pathway were found in the kidney, mainly in renal tubular epithelial cells." (PMID 36977062, 2023). "Pyroptosis via NLRP3 and Caspase-1 was originally described as an antimicrobial response following infection by intracellular pathogens." (PMID 37487005, 2023). "We have previously demonstrated that an aggregated PB1-F2 peptide derived from pathogenic IAV strains induces NLRP3 activation and contributes to disease pathology during infection, suggesting that viral protein aggregates may contribute to the immunopathology and inflammation following infection." (PMID 37950278, 2023). "In this respect, administration of anakinra, a recombinant interleukin-1 receptor antagonist (IL-1Ra), has been proven to reduce NLRP3-driven inflammation and protect against infection in a murine model of VVC." (PMID 37317186, 2023).
infection (continued). "Activation of the NLRP3 inflammasome also directly or indirectly involves proinflammatory response, cell death, and pathogenesis related to infection with other RNA viruses." (PMID 37515138, 2023). "Recent research has demonstrated that following an infection, the spike protein can stimulate the NLRP3 inflammasome by suppressing mitophagy and elevating mtROS production." (PMID 37892135, 2023). "Pyroptosis is mediated by inflammasome sensors such as the NLR family pyrin domain containing 3 (NLRP3) inflammasome, which can be activated by infection, toxins, or intracellular stresses such as mitochondrial ROS and oxidized mitochondrial DNA." (PMID 37691124, 2023). "The NLRP3 inflammasome can be activated by a variety of stimuli during infection, including potassium efflux downstream of caspase-4-dependent GSDMD activation and pore formation (5, –, 9)." (PMID 37615436, 2023). "Upon infection or stimulation, NLRP3, ASC, and pro-caspase-1 assembles to form an inflammasome complex, which activates pro-caspase-1 by cleavage." (PMID 36726689, 2023). "In the later phases of infection, however, it was found that the NLRP3 reduces NF-κB and MAPK signaling, thereby promoting Francisella’s replication inside infected macrophages." (PMID 37841261, 2023). "The qRT-PCR analysis showed that hvKp and cKp infection upregulated the mRNA level of Nlrp3 in BMDMs, which indicates that hvKp and cKp infections enhance the occurrence of pyroptosis via the formation of NLRP3 inflammasome in BMDMs." (PMID 37457695, 2023). "Previous studies have shown that MFN2 acts as a major regulator of the immune response by binding to NLRP3 and promoting IL-1β secretion after infection with the virus." (PMID 36968589, 2023). "Previous studies involving cp-BVDV infection in macrophages have shown that IL-1β secretion is stimulated 24 h post-infection due to the activation of NFкB and that IL-1β maturation is mediated by the NLRP3 inflammasome." (PMID 37515181, 2023). "NLRP3 inflammasome activation is tightly regulated by innate immune molecules during infection and inflammation." (PMID 37300757, 2023). "The signaling of IL‐1β mediated by NLRP3 inflammasome can also recruit NEs for virus clearance and host survival in IV infection." (PMID 37773712, 2023). "Like H. pylori, infection by Mycoplasma hyorhinis (M. hyorhinis, M. hy) fosters IL-1β secretion, which underpins GC cell migration and invasion, in an NLRP3-dependent manner." (PMID 37891577, 2023). "While IL-1β release from ΔexoST infected neutrophils is also NLRC4-dependent, infection with PAO1 is instead NLRP3-dependent and driven by the ADP ribosyl transferase activity of ExoS." (PMID 37730693, 2023). "Despite the known importance of the inflammasome in infection control, there are still unanswered questions about the mechanisms involved in NLRP3 activation in Leishmania-infected macrophages." (PMID 36828815, 2023). "Zhou and colleagues first described the activation of the NLRP3 inflammasome in IL-1β secretion in macrophages after infection by C. pseudotuberculosis." (PMID 36761775, 2023). "Previously published data demonstrated increased activation of the NLRP3 inflammasome, caspase-1, caspase-5, IL-1β, IL-18 and gasdermin D after infection of C. acnes-infected nucleus pulposus tissue." (PMID 36761775, 2023). "This study demonstrated that NLRP3 is crucial for virus clearance at early stages of infection but can induce exaggerated inflammation during later stages of infection." (PMID 37508374, 2023). "Aligned with these results, here we show for the first time that SARS-CoV-2 invasion in the brain following intranasal infection of K18-hACE2 mice, leads to extensive microglial NLRP3 inflammasome activation." (PMID 36316366, 2023). "The results showed that the activation of NLRP3 inflammasome was enhanced after IVA infection in Terc−/− macrophages." (PMID 37817895, 2023).
infection (continued). "RSV induces the activation of the NLRP3 inflammasome and caspase 1, and both events are crucial for the secretion of IL-1β, IL-33, and IL-18 during infection." (PMID 37508374, 2023). "This suggests that the recruitment of ASC during infection with the NADL cp strain in bovine macrophages is dependent on NLRP3." (PMID 37515181, 2023). "Taken together, these results indicate that NLRP3 inflammasome activation is detected during the early steps of human macrophage infection with SARS-CoV-2." (PMID 37920468, 2023). "Consistently, crotonate reduced NLRP3/caspase-1 dependent cleavage of the proinflammatory cytokine interleukin (IL)-1β at 3 and 6 h post-infection." (PMID 37929941, 2023). "At 15 weeks post infection, we detected increased parasite loads in the ears of Gsdmd–/–, Nlrp3–/–, and Casp1/11–/– as compared to WT mice." (PMID 36828815, 2023). "Among them, NLRP3 inflammatory vesicles are present in neurons and glial cells, which are involved in many critical innate immune processes, such as infection and inflammation." (PMID 37492068, 2023). "A large number of studies have shown that the activation of the NLRP3 inflammasome is essential for the host immune response against infections." (PMID 37243164, 2023). "Once SARS-CoV-2 successfully antagonizes immune surveillance and establishes prolonged infection, the NLRP3 inflammasome and signaling cascade is constitutively switched on and triggers cytokine storm, the massive production of proinflammatory cytokines." (PMID 37515138, 2023). "Studies have been conducted that demonstrate that the NLRP3 inflammasome becomes activated upon macrophage infection by Pseudomonas aeruginosa." (PMID 37892135, 2023). "When infection and cellular injury occur, the NLRP3 inflammasome can activate caspase-1 and then induce the activation of the inflammatory cytokines IL-1β and IL-18." (PMID 36713830, 2023). "In this regard, Wan and colleagues indicated that ERK/AP‐1 signaling pathway increases the transcription of pro‐IL‐1β to facilitate the activation of NLRP3 inflammasome upon IV infection." (PMID 37773712, 2023). "They showed that ZBP1 can modulate neutrophil influx and NET formation into the lung via managing necroptotic cell death and controlling NLRP3 activation and IL‐1β release during IV infection." (PMID 37773712, 2023). "For the host immune system to defend itself against external infections, the NLRP3 inflammasome, which belongs to the nucleotide-binding domain leucine-rich repeat family, is necessary." (PMID 36713830, 2023). "We also found that cathepsin B activation is involved in the induction of pyroptosis and NLRP3 inflammasome formation during infection." (PMID 37457695, 2023). "In vitro studies demonstrate that NLRP3-dependent inflammasome activation is detected upon macrophage abortive infection." (PMID 37920468, 2023). "The whole process was driven by infection of mice with Clostridium difficile (C. difficile) to induce NLRP3 inflammasome leading to pyroptosis and IL-1β release through pore forming GSDMD." (PMID 38087059, 2023). "It is reported that this NLRP3 inflammasome is activated upon infection with viruses such SARS-CoV, encephalomyocarditis virus (EMCV), and influenza virus." (PMID 36703213, 2023). "NLRP3 is a group of multiprotein complexes of the inflammasome that are primarily triggered by infection or tissue damage." (PMID 36421808, 2022). "We found 26 proteins that were significantly altered by the CFT073 infection in caspase-1, caspase-4 or NLRP3-knockdown cells compared to CFT073 stimulated Cas9 control cells or compared to their own unstimulated controls." (PMID 35132157, 2022). "We further tested the degree of conformational change in NLRP3 in response to infection by IAV M2 mutants." (PMID 35062292, 2022). "A recent study has also demonstrated that PA infection results in the activation of NLRP3 inflammasome in mice lungs, as indicated by induction of NLRP3 and ASC as well as caspase-1 and IL-1β." (PMID 36463179, 2022).
infection (continued). "Next, we revealed that at the early time point after infection (2 h.p.i.), robust induction of the cytokines, including Ifnb1, Tnfa, Il12b, and inflammasome genes Nlrp3 was obtained, which is consistent with a previous study." (PMID 35604097, 2022). "Collectively, these data suggest that both the NAIP/NLRC4 and NLRP3 inflammasomes control intracellular Salmonella replication within human macrophages at both early (6 hours post-infection) and late (24 hours post-infection) timepoints." (PMID 35073381, 2022). "It has been demonstrated that NLRP3 is activated by SARS-CoV-2 at an early stage of the infection and induces cytokine release syndrome." (PMID 35847031, 2022). "The Western blot results indicated that the NF-κB signaling pathway and NLRP3 inflammasome of CCEC-SV40T cells were activated after infection with S. pseudintermedius." (PMID 35578336, 2022). "Unsurprisingly, considering the present discussion, a previous report had already indicated activation of the NLRP3 inflammasome upon infection with EV71." (PMID 36298668, 2022). "Taken together, these results show that ASFV-ΔH240R infection specifically activates the NLRP3 inflammasome to promote the secretion of IL-1β." (PMID 36326277, 2022). "Our study reveals that SVA infection regulates NLRP3 inflammasome complex assembly and provides a theoretical basis for the control of inflammation during SVA infection." (PMID 35254168, 2022). "Our data reveal a novel mechanism underlying the activation of the NLRP3 inflammasome after SVA 3D expression, which provides clues for controlling pig’s inflammation during the SVA infection." (PMID 35254168, 2022). "Intriguingly, ASFV-ΔH240R infection induced NLRP3 inflammasome activation to promote IL-1β secretion from PAMs." (PMID 36326277, 2022). "NLRP3 has a protective role during infection, being a PRR that triggers processing and secretion of IL-1α." (PMID 35215128, 2022). "We find that although the NAIP/NLRC4 inflammasome is essential for detecting T3SS ligands in human macrophages, it is partially required for responses to infection, as Salmonella also activated the NLRP3 and CASP4/5 inflammasomes." (PMID 35073381, 2022). "In contrast to priming “signal 1”, functional activation of the synthesized NLRP3 inflammasome is mediated by “signal 2”, which is related to infection, cell activation, or cell/tissue damage." (PMID 34984827, 2022). "Upregulation of NLRP3, IL-1β, and IL-18 was also demonstrated in primary isolated human bronchial epithelial cells after a 6-h infection with PAO1." (PMID 35215060, 2022). "There is a single paper that documents activation of the NLRP3 inflammasome after infection with this virus." (PMID 36298668, 2022). "Despite the fact that the RTCs formed by HCV, HRV, and SARS-CoV-2 are morphologically distinct, their infections have been reported to activate NLRP3 inflammasome." (PMID 35758658, 2022). "After this significant indication that SARS-CoV-2 promoted NLRP3 activation, besides the generic infection-associated signals, specific SARS-CoV-2 viral particle-mediated NLRP3 inflammasome activation has also been described on multiple levels." (PMID 35626754, 2022). "Here, we reviewed and discussed the activation mechanisms of NLRP3 inflammasome in neutrophils as well as its functional relevance during infections and inflammatory diseases." (PMID 35406754, 2022). "NOD1, NOD2, and NLR Family Pyrin Domain Containing 3 (NLRP3) are involved in the anti-infection process by activating the NF-κB signaling pathway, type I IFN signaling pathway, autophagy-related pathway, and pyroptosis pathway." (PMID 35197966, 2022). "Previous studies have shown that infection with Schistosoma mansoni, Toxoplasma gondii and Trypanosoma cruzi can activate the NLRP3 inflammasome in host cells." (PMID 36151570, 2022). "Our previous study has revealed the essential role of NLRP3 inflammasome for clearing invading pathogens in moderate infection." (PMID 35982051, 2022).